TNF (tumor necrosis factor)
Diseases named in the same sentence as TNF in open-access papers (continued):
Sharing a sentence is not in itself a finding about the gene and the disease.
tumor (continued). "The results showed that both NO and TNF-α were significantly increased in the tumor-induced group." (PMID 30787353, 2019). "For instance, pre‐treatment with TNFα‐CSG may sensitise inaccessible tumours for better detection as exemplified here by improved uptake of the nanoparticle contrast agent." (PMID 31709774, 2019). "Notably, we observed a sustained high signal of TNFα expression in the residual tumor 9 days after iRFA." (PMID 31780645, 2019). "Moreover, the biological effects of TNFα targeted to tumour ECM were different from those of TNFα targeted to tumour vessels." (PMID 31709774, 2019). "Moreover, since Notch1 activation following TNFα stimulation depended almost entirely on p65 activation, it is highly possible that Notch-mediated regulation of tumor cell migration and invasion was also induced by p65 activation, as result of TNFα activation." (PMID 31105691, 2019). "Overall, our observations suggest that at the TME of TNBC tumors, which is enriched with TNFα and IL-1β, the two pro-inflammatory cytokines regulate tumor-stroma interactions that occur at the tumor site, and that under these conditions the in vivo aggressiveness of the tumor cells is increased." (PMID 31031757, 2019). "Reduction of tumor weight and volume, downregulation of TNF-α and NF-κB expressions." (PMID 31402861, 2019). "In addition, as reported by many authors curcumin also affects other molecular events implicated in the inflammation and the consequent promotion of tumor such as inflammatory cytokines (TNFα, interleukins IL‐1, IL‐6 and IL‐8)." (PMID 31313893, 2019). "Inflammatory cytokines, for example, interleukin-1 beta (IL-1β) and tumor necrosis factor alpha (TNF-α) secreted by immune cells could be acting as chemoattractants for MSCs chemotaxis to tumor sites." (PMID 31130595, 2019). "VEGF blockade also substantially enhanced TNF-α expression in relapsing tumor cells." (PMID 31829270, 2019). "Multiple mechanisms may be involved in the increased antitumor capability of TNF-α-treated tumor specific Th9 cells." (PMID 30717817, 2019). "Our above findings motivated us to determine whether the pro-inflammatory signals delivered by TNFα to TNBC:MSC “Contact” co-cultures in vitro would potentiate tumor growth or metastasis in an animal model system." (PMID 31031757, 2019). "To further analyse whether CAR-147 macrophage reinfusion causes cytokine storms like CAR-T cell infusion does, we detected the cytokines IL-1β, IL-6, IL-12, TNFα, and IFNγ in serum samples and tumour homogenates." (PMID 31570753, 2019). "We hypothesised that TNFα, when specifically targeted to tumour ECM, may have similar effects, leading to ECM degradation and enhanced penetration of compounds to tumours." (PMID 31709774, 2019). "We show that ECM reduction by TNFα‐CSG alleviates tumour stiffness, reduces vessel compression, increases vessel dilation and may facilitate further increases in immune cell infiltration." (PMID 31709774, 2019). "In addition to RIP1‐Tag5 and 4T1 tumours, TNFα‐CSG (5 daily i.v. injections of 5 μg) also improved immune T‐cell infiltration into ALB‐Tag HCC (Fig EV3D)." (PMID 31709774, 2019). "Upon activation, NK cells attack tumor cells through releasing cytotoxic perforin and granzyme and activating apoptosis in tumor cells through the production of IFNγ and TNF or via direct cell contact through death receptor-mediated pathways such as the TRAIL and FASL pathways." (PMID 32039025, 2019). "We provide evidence that this effect is due to tumor tropism via hijacking the tumor microtube network for selective drug transfer, induction of TNF-α release, and suppression of Dox-induced tumor invasion resulting in massive tumor cell apoptosis and superior survival benefits." (PMID 31660078, 2019). "MDSCs can secrete IL-6 and TNF-α, which can promote tumor growth." (PMID 31832112, 2019).
tumor (continued). "In addition to GM-CSF and TNF-α, MC also store and release several other potential anti-tumor mediators including reactive oxygen species (ROS), prostaglandin D2 (PGD2), interleukin-9 (IL-9), and heparin." (PMID 30833944, 2019). "Substantial evidence has accumulated demonstrating TNF’s pro-tumor effects in animal models." (PMID 31174326, 2019). "Given the presence and important roles for TNF‐α and GM‐CSF in the tumor microenvironment and the host response to cancer, it is very likely that the changes in neutrophil signaling and function induced by these ligands, and the process of priming, shape tumor progression." (PMID 30720883, 2019). "Thus, ECM content in normal exocrine tissue surrounding the tumours was unaffected by TNFα‐CSG treatment (shown for laminin in Fig EV5A)." (PMID 31709774, 2019). "To study if hMSCs could release cytokines in vivo, we measured the expression of TNF-α and IL-6 in tumor tissues by real-time PCR." (PMID 31142737, 2019). "TNF (tumor necrosis factor) has an important role in the tumor microenvironment." (PMID 31861498, 2019). "Next, to examine whether Bai could reprogram macrophages toward an M1-like phenotype, leading to tumor suppression, we measured the presence of IL-6 and TNF-α in the supernatant of RAW264.7 cells following treatment with Bai." (PMID 31777307, 2019). "Finally, it was confirmed that the bioactive compounds of compound Liuju formula have not only a killing effect on NSCLC tumor cells but also a synergistic effect on inhibiting the secretion of correlative inflammatory mediators, including TNF-α and IL-1β." (PMID 31949474, 2019). "The anti-tumor activity exerted by CD8+ T-cells was not a result of the degranulation of CD8+ cells, and thus, apoptosis pathways via TNF-α or Fas may have been involved in the anti-tumor effects." (PMID 31105882, 2019). "Transmembrane TNFα functions as both ligand and receptor: soluble TNFRs can bind to the cytokine on the cell surface and generate reverse signaling, leading to immunity and anti-tumor effects." (PMID 31557902, 2019). "Furthermore, this approach also increased cytokine production in the tumor region, including that of IL-1β, TNF-α, IFN-γ, and GM-CSF49." (PMID 31827064, 2019). "Tumor necrosis factor alpha (TNF-α) could promote tumor growth via a PKCa- and AP-1-dependent pathway." (PMID 31552191, 2019). "In the cancer setting, a similar phenomenon occurs as tumor-infiltrating T cells upregulate multiple co-inhibitory receptors and are limited in their ability to produce multiple effector cytokines (such as IFNγ and TNFα), making them less polyfunctional and unable to clear the tumor." (PMID 31244852, 2019). "Moreover, tumor-derived TNF-α efficiently induces programmed death-ligand 1 (PD-L1) expression on mast cells by activating nuclear factor kappa-light-chain-enhancer of activated B cells (NF-κB) signaling pathways." (PMID 30808413, 2019). "Our study revealed that Sal-B reduced tumor tissue TNF-α levels induced by ESC." (PMID 31726654, 2019). "The exposure of tumor cells to certain important cytokines like IFNγ, TNFα, and IL-1 was shown to increase ROS production by tumor cells themselves in various cancer types, while the elevated ROS levels were attributed to NOX elevation or mitochondria activity." (PMID 30935064, 2019). "One study designed HA-based combination adjuvant systems by combining HA with immunostimulatory compounds (HA; Mw = 500–1300 kDa), showing anti-tumor therapeutic effects by prevention of tumor proliferation and a significant increase in the cytokine secretion of IL-6 and TNF-α." (PMID 31266194, 2019). "TNF is known as a circulating element leading to tumor necrosis." (PMID 31205938, 2019). "The main source of TNF-α is activated macrophages and monocytes, moreover, some other cells, such as lymphocytes, polymorphonuclear leukocytes, keratinocytes, and tumor cells, may also secrete TNF-α." (PMID 31652851, 2019).
tumor (continued). "In this study, we evaluated the expression of CCL2, IL18, TNF-α, and IL23α, and whether they play a role in tumor progression or suppression." (PMID 32695310, 2019). "Moreover, our findings emphasized the contribution of TNFα to the angiogenic potential revealed by tumor cells grown in the presence of stromal cells." (PMID 31031757, 2019). "In particular, a subset of high Interferon -γ (IFN-γ) secreting NK cells is at the forefront of innate response against cancer and it is responsible for Tumor Necrosis Factor (TNF)-related apoptosis-inducing ligand (TRAIL)-dependent lysis of tumor cells in mice." (PMID 31812953, 2019). "In this model, tumor infiltrating macrophages, NK cells and T cells secreting IFNγ and TNFα and expressing TRAIL were responsible for suppression of lung metastases since neutralizing TRAIL antibodies blocked antitumor activity leading to increased lung metastases." (PMID 31333662, 2019). "In addition, ADAM17 protein is responsible for the activation of TNFα, initiating the signaling pathway associated with the EGF receptor for which it is a ligand, leading to tumor cell proliferation." (PMID 31565100, 2019). "TNF-α has anti-inflammation effects, inhibiting or killing tumor cells." (PMID 31308853, 2019). "Notably, in EOC models of peritoneal dissemination, where human tumor cells grown in mouse peritoneum constitutively secrete TNFα, genetic attenuation of TNFα expression in tumor cells significantly decreased carcinoma burden." (PMID 31817625, 2019). "TNFα is a frequently identified, soluble, tumor-suppressing factor in cancerous microenvironments." (PMID 31681332, 2019). "This is in marked contrast to stimulation by a single agent, which achieved the greatest increases in IFN-γ, TNF-α, and IL-2 secretion as well as the greatest increase in T-lymphocyte proliferation and the greatest enhancement of tumor cell lytic activity in vitro." (PMID 31694582, 2019). "TNF-α can also stimulate the transcription of genes encoding endothelial cell adhesion molecules, including E selectin, ICAM-1, VCAM-1, and Madcam1, which are closely related to tumor metastasis and angiogenesis." (PMID 31600735, 2019). "TNF-α treatment generally increased adhesion ability of the tumour cells." (PMID 31565662, 2019). "The microenvironment of most tumors is highly enriched with TNF producing cells such as macrophages, T cells, and fibroblasts and often contains increased Treg numbers that crucially contribute to tumor immune escape and tumor progression." (PMID 31555271, 2019). "Tumor necrosis factor (TNF) was first described in 1975 as a serum factor that could lyse tumor cells present in bacillus Calmette-Guerin (BCG)-infected mice that were challenged with endotoxin." (PMID 31457011, 2019). "IFN-γ and TNF-α play important roles in cytotoxic T cell functions and anti-tumor activity." (PMID 31013891, 2019). "TNF-α has also been proven to possess anti-tumor effects through various mechanisms." (PMID 30600678, 2019). "Tim-3 and TNF-α mRNA levels in tumor tissues were measured in both humans and mice." (PMID 31109341, 2019). "Our observation that tumor-infiltrating NKT cells showed lower expression of IFN-γ, TNF-α, and GM-CSF as compared to splenic counterpart suggests that tumor microenvironment may induce changes in NKT cells." (PMID 31387637, 2019). "Likewise, cytokines such as IL-1β, IL-4, IL-13 and TNF-α facilitate the cell fusion process that results in increased tumour-hybrid formation." (PMID 31266502, 2019). "However, when immune cells infiltrate the tumor mass, this activity inverts, and the production of TNF-α benefits to the tumor progression." (PMID 31485295, 2019). "Also, NF-κB regulates the expression of several important genes, such as COX-2, iNOS, TNF-α and cell surface adhesion molecules, which are involved in tumor initiation, promotion, and metastasis." (PMID 31223464, 2019).
tumor (continued). "Moreover, much of the invasive advantages that were endowed to the tumor cells by their co-culturing with MSCs in the context of TNFα stimulation, were inhibited by DAPT." (PMID 31105691, 2019). "Moreover, CD8+ T cells selectively accumulated in ECM‐rich zones in the TNFα‐CSG‐treated tumours (Fig EV3A)." (PMID 31709774, 2019). "Additionally, TNFα increases activation-induced cell death in T cells, limiting their viability in the tumor microenvironment." (PMID 31439050, 2019). "Moreover, our findings establish that niclosamide potentiates anti-PD-L1 blockade response in vitro as well as in syngeneic tumor models, which correlates with an increased content of TILs and enhanced secretion of Granzyme B and TNF-α from cytotoxic T cells." (PMID 31511071, 2019). "Thus, iNOS and TNF-α were shown to promote tumor proliferation, angiogenesis, invasiveness, and metastasis." (PMID 30984181, 2019). "One way to achieve this goal may be represented by the administration of small molecule inhibitors of key components in the TNF signaling pathway, building up activity at the tumor site, while decreasing systemic toxicity." (PMID 31803362, 2019). "In addition, TNF, a major inflammatory cytokine, is known to participate in many steps of carcinogenesis and tumor progression." (PMID 30699951, 2019). "Here, we show that TNFα‐CSG therapy improves the tumour accumulation of IONPs." (PMID 31709774, 2019). "CD8+ Tcells effect tumor killing in two ways; (i) through the secretion of cytotoxic molecules (granzyme B and perforin) and, (ii) through the secretion of proinflammatory cytokines (IL-2, TNF-α, and IFN-g)." (PMID 30979375, 2019). "The authors reported a delay in tumor growth, an influx of lymphocytes and NK cells into the tumors, and, in the tumor microenvironment, reduced levels of the suppressive cytokines IL-10 and TGFβ, and increased levels of IL-2 and TNFα." (PMID 31588231, 2019). "Furthermore, deregulated expression of TNF-alpha in the micro-environment of a tumor seems to promote tumoral invasion and migration and subsequently metastasis." (PMID 30696421, 2019). "It is widely known that TNFα upregulation may induce changes in the tumor vasculature and stimulate the antitumor immune response." (PMID 31861531, 2019). "Tumor necrosis factor is a proinflammatory cytokine with pro- and anti-tumor effects." (PMID 31174326, 2019). "This unique role may be related to the rapid increase in TNFα production upon tumor cell entry into the liver, as we and others have documented and may contribute to the liver-specific consequences of ovariectomy, noted in this study." (PMID 31848339, 2019). "Additional studies are however warranted in order to investigate if, similarly to that has been observed in vitro, in vivo hVCAM-1 expression in MDA-MB-231 tumor cells can be increased by TNF-α or other cytokines present in the microenvironment, leading to increased 99mTc-cAbVCAM1-5 uptake." (PMID 31340603, 2019). "Therefore, we further measured the expression of IL-6 and TNFα in tumor tissues in mRNA level and found that the expression of IL-6 and TNF-α were higher in HCC-hMSCs group." (PMID 31142737, 2019). "Since high TNF-α levels and Pgp expression are related to metastasis formation in different types of cancer, our results suggest that Pgp and TNF-α carried by MP could induce transformation of adjacent non-tumor cells." (PMID 31137684, 2019). "Additionally, activated CD8+ T cells release IFN-γ and tumor necrosis factor alpha (TNF-α) to induce cytotoxicity in the target cells and stimulate M1 macrophage-mediated anti-tumor response." (PMID 31181772, 2019). "Anti-TNF-α blockade has shown interesting anti-tumor effects." (PMID 31544819, 2019). "Low levels of TNFα in the TME may lead to monocyte differentiation into a macrophage phenotype that promotes local tumor growth, angiogenesis, and immune escape." (PMID 31022866, 2019). "The authors postulated that macrophage derived TNF mediated the anti-tumor effects." (PMID 31174326, 2019).
tumor (continued). "TNFα has both anti-tumor effects mainly by activating apoptotic pathways and pro-tumorigenic effects such as cell survival, angiogenesis, and EMT by activating MAPK and NF-κB signaling pathways leading to inflammatory responses, acting in an autocrine or paracrine manner." (PMID 31557902, 2019). "Finally, cytokines typically present within the tumor microenvironment, such as TNF, IL-1, and IL-6, have been shown to increase ST6Gal-I expression." (PMID 31610800, 2019). "Furthermore, TNFα armed viruses have seen success in inducing tumor regression and vascular collapse in solid masses when administered in tumor-bearing mice alongside therapies that inhibit anti-apoptosis proteins in vitro." (PMID 30941125, 2019). "Among the cytokines released by LF-IC-primed human monocytes, TNFα could induce cell death of tumor cells." (PMID 31600968, 2019). "Notably, disruption in the STAT3 signaling pathway effectively promotes anti-tumor immunity by enhancing the production of TNF-α and stimulation of M1-like reprogramming of macrophages." (PMID 31569687, 2019). "Detailed analyses of adoptively transferred CD4+ T cells during tumor challenge revealed the expression of granzyme B, FasL, TNF-α, and IFN-γ in such T cells that might be involved in the antitumour activity." (PMID 31183361, 2019). "This increase in TNF-α levels in the tumor-afflicted mice could be due to a rise in macrophage-produced ROS, which increases lipid peroxidation." (PMID 30755785, 2019). "Via its type 1 and type 2 receptors (TNFR1 and TNFR2), TNF-α may activate apoptosis, inhibit tumor growth, or promote tumor invasion, propagation, and aggressive behavior." (PMID 31093512, 2019). "M1 macrophages act in microbiocidal and anti-tumor activity with the secretion of IL1β, IL12 and TNF-α, whereas M2 macrophages act in tissue remodeling, immune tolerance and tumor progression with the secretion of IL4, IL10 and transforming growth factor (TGF)-β." (PMID 31408948, 2019). "The proinflammatory cytokine TNF-α is involved in the tumor–epithelial cell fusion." (PMID 31380426, 2019). "Taking these findings together, the 1,2-DHX-dependent increase in TNF-α and decrease in IL-10 detection may contribute to tumor regression, although the TGF-β1 increase seems to contradict the xanthone antitumor effects." (PMID 31167479, 2019). "Therefore, TNF-α plays an important role in tumor proliferation, angiogenesis, invasion, and metastasis." (PMID 31500658, 2019). "Another important difference observed was a reduction in the proportion of cell death within total and antigen-specific CD8+ T cells in the tumor microenvironment and dLN of mice as a result of systemic TNF neutralization, suggesting an attenuation of the activation-induced cell death (AICD)." (PMID 31309173, 2019). "Selective targeting of tumor (vs. normal) vasculature was documented through serial biopsy of tumor and proximate normal tissues after intravenous infusion, and tumor-directed expression of TNF was documented." (PMID 31803625, 2019). "The chlorine e6 and doxorubicin-loaded hollow manganese dioxide nano platform (H-MnO2-PEG/C&D) can relieve tumor suppression whereas checkpoint-blockade (PD-L1 blockade) promotes the higher TNF-α secretion and augmented CD4+ and CD8+ T cells-mediated immune response than chemo-PDT therapy." (PMID 31754376, 2019). "Metastatic cell co-culture exhibited 10× higher TNF-α induction than with primary tumor cells." (PMID 31636296, 2019). "NK cells are the main effector cells from the innate immune response and eliminate aberrant tumor cells by granule release (perforin/granzyme) dependent toxicity and via membrane receptor interactions involving FasL, TNFα, and TRAIL depending on their differentiation and activation status." (PMID 31333662, 2019). "The mean tumour stiffness remains unchanged in response to TNFα‐CSG treatment." (PMID 31709774, 2019).